RNU6-1186P (RNA, U6 small nuclear 1186, pseudogene)
Gene: Small nuclear RNA gene on chromosome 15 (98,074,667 to 98,074,763, reverse strand). Ensembl gene ENSG00000222361.
Homologues: Orthologues: chimpanzee U6 (100% identical), macaque U6 (98% identical), dog U6 (80% identical), guinea pig U6 (73% identical), rat LOC120094405 (73% identical), mouse Gm24399 (57% identical). Paralogues in human: RNU6-1011P (81% identical), RNU6-1145P (81% identical), RNU6-20P (81% identical), RNU6-38P (81% identical), RNU6-26P (80% identical), RNU6-41P (80% identical), RNU6-477P (80% identical), RNU6-621P (80% identical), RNU6-737P (80% identical), RNU6-12P (79% identical), RNU6-1314P (79% identical), RNU6-1316P (79% identical), and 1285 more.